TACR2 (tachykinin receptor 2)
Description:
This is a receptor for the tachykinin neuropeptide substance K (neurokinin A). Is also able to bind and respond to tachynins substance P and neurokinin B/neuromedin-K (By similarity). The rank order of affinity of this receptor to tachykinins is: substance K > neuromedin-K > substance P (By similarity). Substance K binding to its receptor triggers G protein-coupled receptor signaling via activation of G(q) and phosphatidylinositol hydrolysis by phospholipase C. Substance K binding also triggers signaling via activation of adenylate cyclase activity which results in increased intracellular levels of cyclic AMP (cAMP) (By similarity).
Synonyms: SKR; NK2R; NKNAR; TAC2R
Tractability: Small molecule: a drug acting on it is in phase 2 or 3 trials; a high-quality ligand is known; it belongs to a druggable protein family. Antibody: its Gene Ontology location is reachable by antibodies, with high confidence; UniProt places it where antibodies can reach, with medium confidence; UniProt predicts a signal peptide or a membrane-spanning region; the Human Protein Atlas places it where antibodies can reach. PROTAC: a small molecule that binds it is known. Other modalities: a drug acting on it is in phase 2 or 3 trials.
Target class: Membrane receptor; Short peptide receptor (family A GPCR); Neurokinin receptor; Family A G protein-coupled receptor; Peptide receptor (family A GPCR)
Chemical probes: NEUROKININ A, SAREDUTANT (high quality)
Safety:
Unwanted effects reported when the protein is acted on. In parentheses: how it was acted on, where the effect was seen, and who reports it.
bronchoconstriction (activation, acute dosing; immune, gonad, gastrointestinal; source: Lynch et al. (2017))
decreased anxiety (inhibition, acute dosing; immune, gonad, gastrointestinal; source: Lynch et al. (2017))
decreased inflammation (inhibition, acute dosing; immune, gonad, gastrointestinal; source: Lynch et al. (2017))
decreased intestinal transit (inhibition, acute dosing; immune, gonad, gastrointestinal; source: Lynch et al. (2017))
decreased pain (inhibition, acute dosing; immune, gonad, gastrointestinal; source: Lynch et al. (2017))
delayed/absent sexual maturity (inhibition, acute dosing; immune, gonad, gastrointestinal; source: Lynch et al. (2017))
increased intestinal transit (activation, acute dosing; immune, gonad, gastrointestinal; source: Lynch et al. (2017))
increased urinary bladder contractions (activation, acute dosing; immune, gonad, gastrointestinal; source: Lynch et al. (2017))
testicular degeneration (inhibition, acute dosing; immune, gonad, gastrointestinal; source: Lynch et al. (2017))
Gene: Protein-coding gene on chromosome 10 (69,403,903 to 69,416,918, reverse strand). Ensembl gene ENSG00000075073.
Subcellular location: Cell membrane
Subcellular location (Human Protein Atlas): Plasma membrane
Pathways (Reactome):
Signal Transduction: G alpha (q) signalling events; Tachykinin receptors bind tachykinins
Gene Ontology:
Molecular function: protein binding; substance K receptor activity; tachykinin receptor activity; G protein-coupled receptor activity
Biological process: positive regulation of flagellated sperm motility; adenylate cyclase-activating G protein-coupled receptor signaling pathway; muscle contraction; phospholipase C-activating tachykinin receptor signaling pathway; positive regulation of smooth muscle contraction; tachykinin receptor signaling pathway; G protein-coupled receptor signaling pathway; intestine smooth muscle contraction; negative regulation of luteinizing hormone secretion; operant conditioning; positive regulation of acetylcholine secretion, neurotransmission; positive regulation of monoatomic ion transport; positive regulation of uterine smooth muscle contraction; positive regulation of vascular permeability; prolactin secretion; regulation of smooth muscle contraction; regulation of uterine smooth muscle contraction; response to electrical stimulus
Cellular component: plasma membrane; sperm flagellum; sperm head; sperm midpiece; membrane
Genetic constraint (gnomAD): Loss-of-function variants: 26 observed, 32.05 expected, observed/expected ratio (o/e) 0.81, 90% interval 0.59 to 1.13. The upper end of that interval is the gene's LOEUF score, 1.13, which puts it in group 4 of 6, group 1 being the genes least tolerant of losing a copy. Missense variants: 470 observed, 519.74 expected, observed/expected ratio (o/e) 0.9, 90% interval 0.84 to 0.98. Synonymous variants: 214 observed, 213.37 expected, observed/expected ratio (o/e) 1, 90% interval 0.9 to 1.12.
Homologues: Orthologues: chimpanzee TACR2 (98% identical), macaque TACR2 (95% identical), guinea pig TACR2 (86% identical), rabbit TACR2 (85% identical), rat Tacr2 (84% identical), dog TACR2 (83% identical), pig TACR2 (83% identical), mouse Tacr2 (82% identical), zebrafish tacr2 (51% identical), Drosophila melanogaster TkR99D (36% identical), Drosophila melanogaster TkR86C (31% identical), Caenorhabditis elegans tkr-2 (28% identical). Paralogues in human: TACR3 (50% identical), TACR1 (48% identical), GPR83 (25% identical), NPY1R (24% identical), NPY2R (24% identical), PRLHR (23% identical), NPY4R (22% identical), NPY4R2 (22% identical), PROKR2 (20% identical), PROKR1 (20% identical), MTNR1B (19% identical), MCHR1 (19% identical), and 21 more.
Diseases named in the same sentence as TACR2 in open-access papers:
TACR2 is named in the same sentence as 34 diseases in open-access papers, as found by Europe PMC text mining. Sharing a sentence is not in itself a finding about the gene and the disease. The quoted sentences say what the papers report.
colitis (4 papers, 2008 to 2025). Inflammation of the colon. "Although this composite profile resembles that observed in inflammatory bowel disease, Tacr2 deletion conferred resistance to DSS-induced colitis in males." (PMID 41332647, 2025).
prostate carcinoma (2 papers, 2020 to 2021). A carcinoma that arises from epithelial cells of the prostate gland. "Recent microarray analysis for prostate cancer suggests that TACR2 expression is associated with clinical phenotype and disease-free survival among patients with prostate cancer." (PMID 34364377, 2021). "We found that TACR2 expression levels were low in tissues adjacent to prostate cancer and were higher in patients with higher clinical stages and higher Gleason scores (P < 0.001)." (PMID 34364377, 2021). "Consistent with the TCGA database, expression levels of TACR2 protein in prostate cancer tissues were significantly lower than in adjacent tissues (P < 0.01)." (PMID 34364377, 2021). "Overexpression of TACR2 promoted the migration and proliferation of prostate cancer cells by regulating the Wnt signaling pathway." (PMID 34364377, 2021). "Consistent with the data analysis, the expression of TACR2 protein in prostate cancer tissues was significantly lower, while the expression of β-catenin was significantly higher." (PMID 34364377, 2021). "In this study, we determined the effect of TACR2 on the immune microenvironment of prostate cancer by examining the content of immune cells." (PMID 34364377, 2021). "In conclusion, TACR2 is expressed at low levels in prostate cancer tissue and inhibits prostate cancer cells’ migration and proliferation via the Wnt/β-catenin signaling pathway." (PMID 34364377, 2021). "In the survival analysis with disease-free recurrence as the follow-up endpoint, TACR2 high-expressing prostate cancer patients had better survival outcomes than low-expressing patients (P < 0.001)." (PMID 34364377, 2021). "Of these, TACR2 expression was significantly downregulated in prostate cancer, clear cell renal cell carcinoma, chromophobe tumor, and papillary renal cell carcinoma." (PMID 34364377, 2021). "Using the TIMER database, we found that the expression of TACR2 was significantly downregulated in a variety of cancer tissues, including prostate cancer, clear cell renal cell carcinoma, chromophobe tumor, and papillary renal cell carcinoma." (PMID 34364377, 2021). "TCGA database analysis showed that transcription levels of TACR2 were significantly different between prostate cancer and adjacent normal tissues." (PMID 34364377, 2021). "We used a wound-healing migration assay and a Transwell assay to determine the role of TACR2 in prostate cancer cell migration." (PMID 34364377, 2021). "Further cell function experiments showed that overexpression of TACR2 inhibited the activity, proliferation, and migration of prostate cancer cells." (PMID 34364377, 2021). "Western blot was used to measure expression levels of TACR2 protein in 30 pairs of prostate cancer and adjacent normal tissues." (PMID 34364377, 2021). "The TACR2-Wnt/β-catenin signaling pathway is critical in prostate cancer." (PMID 34364377, 2021). "TACR2 is expected to be a target for immunotherapy of prostate cancer." (PMID 34364377, 2021). "These trends suggest that TACR2 expression is a prognostic protective factor for prostate cancer." (PMID 34364377, 2021). "TACR2 protein levels were lower in prostate cancer tissues than in adjacent normal prostate tissue." (PMID 34364377, 2021). "In addition, we found that TACR2 may affect the migration and proliferation of prostate cancer cells by regulating the Wnt/β-catenin signaling pathway." (PMID 34364377, 2021). "In a previous study, we established and validated a prognostic risk score formula called CMU5 based on the expression of five genes: FAM72D, ARHGAP33, TACR2, PLEK2, and FA2H; the signature reliably predicted prostate cancer outcome." (PMID 34364377, 2021). "FAM72D, ARHGAP33, TACR2, PLEK2, and FA2H were identified as independent prognosis factors in prostate cancer patients." (PMID 32566639, 2020).
breast carcinoma (1 paper, 2023). "Alterations in the expression profiles of TACR2 and TACR3 genes have been reported for different pathologies, e.g., polycystic ovarian syndrome, leiomyoma, oral carcinoma, or breast cancer." (PMID 36980580, 2023).
gastric cancer (1 paper, 2024). A primary or metastatic malignant neoplasm involving the stomach. "Additionally, in gastric cancer, high expression of ankyrin repeat and SOCS box-containing 5 (ASB5), secreted frizzled-related protein 1 (SFRP1), SMYD1, and tachykinin receptor 2 (TACR2) is associated with short survival times and high risk in these patients." (PMID 39482529, 2024).
tumor (8 papers, 2016 to 2024). "Nevertheless, the specific mechanisms of TACR2 and the Wnt/β-catenin signaling pathway and the mechanism of regulating the tumor microenvironment require further study." (PMID 34364377, 2021). "TACR2 may affect tumor cells’ occurrence and development by changing the content of immune cells in the tumor microenvironment." (PMID 34364377, 2021). "The upregulation of TLR3 (3.79×) and CD36 (2.73×), two general tumor markers, and SERPINEB9 (11.37×), FNDC1 (7.58×), and TACR2 (8.84×), three factors of tumorigenesis, confirms the wider pathological significance of this bacterium." (PMID 38787238, 2024).
cancer (6 papers, 2018 to 2023). A tumor composed of atypical neoplastic, often pleomorphic cells that invade other tissues. "Overexpression of TACR2 can develop the proliferation and migration of cancer cells by regulating the Wnt signaling pathway." (PMID 34446027, 2021). "Nevertheless, the role of TACR2 in cancer progression remains unclear." (PMID 34364377, 2021). "To explore the expression pattern of TACR2, we used the TIMER database to determine that TACR2 expression was significantly downregulated in a variety of cancer tissues." (PMID 34364377, 2021).
TACR2 also shares sentences with these, for which no sentence is quoted: asthma (5 papers); Obesity (5); colorectal cancer (2); metabolic disease (2); acute myeloid leukemia (1); airway hyperresponsiveness (1); benign smooth muscle tumor (1); clear cell renal cell carcinoma (1); colon cancer (1); depression (1); endometritis (1); infection (1); inflammatory bowel disease (1); Insulin resistance (1); leiomyoma (1); leukemia (1); liver cancer (1); lymph node metastasis (1); metastatic cancer (1); migrainous headache (1); myeloid leukemia (1); neuroblastoma (1); occupational asthma (1); pancreatic cancers (1); papillary renal cell carcinoma (1); periodontitis (1); Pruritus (1); Sepsis (1).